TPI1 (triosephosphate isomerase 1)
Description:
Triosephosphate isomerase is an extremely efficient metabolic enzyme that catalyzes the interconversion between dihydroxyacetone phosphate (DHAP) and D-glyceraldehyde-3-phosphate (G3P) in glycolysis and gluconeogenesis. It is also responsible for the non-negligible production of methylglyoxal a reactive cytotoxic side-product that modifies and can alter proteins, DNA and lipids.
Synonyms: TIM; TPI; HEL-S-49; TPID
Tractability: Small molecule: a structure with a bound ligand is known. PROTAC: UniProt records ubiquitination sites on it; ubiquitination databases record sites on it; its protein half-life has been measured; a small molecule that binds it is known.
Target class: Enzyme
Gene: Protein-coding gene on chromosome 12 (6,867,119 to 6,870,948, forward strand). Ensembl gene ENSG00000111669.
Subcellular location: Cytoplasm
Subcellular location (Human Protein Atlas): Nucleoplasm
Pathways (Reactome):
Metabolism: Gluconeogenesis; Glycolysis
Gene Ontology:
Molecular function: protein binding; protein homodimerization activity; triose-phosphate isomerase activity; ubiquitin protein ligase binding; methylglyoxal synthase activity; isomerase activity
Biological process: glyceraldehyde-3-phosphate biosynthetic process; canonical glycolysis; gluconeogenesis; glycolytic process; methylglyoxal biosynthetic process; glyceraldehyde-3-phosphate metabolic process
Cellular component: extracellular exosome; extracellular region; nucleus; cytosol; cytoplasm
Genetic constraint (gnomAD): Loss-of-function variants: 11 observed, 32.33 expected, observed/expected ratio (o/e) 0.34, 90% interval 0.21 to 0.56. The upper end of that interval is the gene's LOEUF score, 0.56, which puts it in group 2 of 6, group 1 being the genes least tolerant of losing a copy. Missense variants: 245 observed, 328.36 expected, observed/expected ratio (o/e) 0.75, 90% interval 0.67 to 0.83. Synonymous variants: 121 observed, 127.49 expected, observed/expected ratio (o/e) 0.95, 90% interval 0.82 to 1.1.
Homologues: Orthologues: chimpanzee TPI1 (100% identical), macaque TPI1 (99% identical), dog TPI1 (98% identical), rabbit TPI1 (98% identical), guinea pig TPI1 (98% identical), mouse Tpi1 (96% identical), pig TPI1 (95% identical), rat Tpi1l1 (94% identical), rat Tpi1l2 (94% identical), tropical clawed frog tpi1 (84% identical), zebrafish tpi1b (82% identical), zebrafish tpi1a (80% identical), and 2 more.
Diseases named in the same sentence as TPI1 in open-access papers:
TPI1 is named in the same sentence as 142 diseases in open-access papers, as found by Europe PMC text mining. Sharing a sentence is not in itself a finding about the gene and the disease. The quoted sentences say what the papers report.
breast cancer (25 papers, 2012 to 2026). A primary or metastatic malignant neoplasm involving the breast. "For instance, RELA-bound genes such as NOP10, a member of the H/ACA small nucleolar RNP (snoRNP) gene family, and TPI1, an important glycolytic enzyme are associated with poor prognosis in breast cancer." (PMID 39418101, 2024). "TPI1 is abnormally expressed in different kinds of cancers, such as breast cancer, gastric cancer, and lymphoma and is associated with a poor prognosis in patients with neuroblastoma and pancreatic cancer through dysregulating glycometabolism." (PMID 33344071, 2020). "In the process of glycolytic reprograming, TPI1, one of the key enzymes, have been shown to be closely associated with the deterioration of many cancers, such as intrahepatic cholangiocarcinoma, pancreatic cancer, breast cancer, and lung cancer." (PMID 38102653, 2023). "RESULTS: TCGA database indicated highly expressions of OTUB2, EIF4A3, and TPI1 in breast cancer tissues and TNBC tissues." (PMID 41857621, 2026). "METHODS: We utilized The Cancer Genome Atlas (TCGA) dataset to analyze the expressions of OTUB2, EIF4A3, and TPI1 in breast cancer tissues and specifically in triple-negative breast cancer (TNBC) tissues." (PMID 41857621, 2026). "Upregulation of TPI1 has been reported in breast cancer, lung cancer, gastric cancer, and pancreatic cancer." (PMID 39997396, 2025). "Triosephosphate isomerase (TPI1) is upregulated in neoplasms like gastric or breast cancer and is related to cell migration and invasion." (PMID 39201484, 2024). "Among the genes of the five proteins selected, GPI, LDHA, TPI1, and ALDOA showed high expression in both breast cancer and colorectal cancer and were associated with poor patient prognosis." (PMID 38419074, 2024). "High TPI1 expression is often inversely related to clinical outcomes in lung adenocarcinoma, laryngeal squamous cell carcinoma, breast cancer, Ewing’s sarcoma, and cholangiocarcinoma." (PMID 38667328, 2024). "So, we cannot conclude that TPI1 has different effects on different molecular subtypes of breast cancer." (PMID 35509067, 2022). "It has been found that TPI1 is upregulated in a variety of tumors, including breast cancer, gastric cancer, and lung cancer." (PMID 35246510, 2022). "Our study, for the first time, demonstrates the roles of TPI1 in promoting breast cancer progression, and provides a new strategy for targeted glycolysis therapy." (PMID 35509067, 2022). "Additionally, TPI1 promotes the progression of breast cancer cells by regulating cell division cycle proteins and activating phosphoinositide 3-kinase/AKT serine/threonine kinase 1/mammalian target of rapamycin pathway." (PMID 38102653, 2023). "However, in our study, TPI1 is overexpressed in breast cancer, while p62 promotes degradation of TPI1." (PMID 35509067, 2022). "P62 and TPI1 are expressed differently in different molecular types of breast cancer." (PMID 35509067, 2022). "However, expression profile and regulatory mechanism of TPI1 in breast cancer (BRCA) remain mysterious." (PMID 35509067, 2022). "However, higher levels of autoantibodies against TPI1 have been reported in the sera of breast cancer patients." (PMID 22664934, 2012). "More importantly, glycolysis enzymes (GPI, LDHA, TPI1, and ALDOA) were significantly enriched in the exosomes of primary tumors of both canine mammary tumor and human colorectal tumor, compared to metastases." (PMID 38419074, 2024). "Mechanistically, through stabilizing CDCA5, TPI1 activates PI3K/AKT/mTOR pathway, which in turn promotes breast cancer metastasis and glycolysis." (PMID 35509067, 2022). "The highest frequency of antibodies to an individual TAA in breast cancer was against A1AT (83.3%) and TPI1 (66.7%), followed by PPIA (58.3%) and PRDX2 (50%)." (PMID 33096879, 2020).
gastric cancer (17 papers, 2010 to 2025). A primary or metastatic malignant neoplasm involving the stomach. "Salivary proteins cystatin B (CSTB), triosephosphate isomerase (TPI1), and deleted malignant brain tumors 1 protein (DMBT1) have all been associated to gastric cancer." (PMID 40005360, 2025). "For example, TPI1 suppresses HCC cell growth and motility while high TPI1 level has been shown to be associated with gastric cancer." (PMID 34401050, 2021). "The prognostic value TPI1 was also evaluated in gastric cancer, where patients with higher TPI1 expression had lower overall survival." (PMID 32197468, 2020). "In this pathway, G3P is first converted into dihydroxyacetone phosphate (DHAP), a reaction catalyzed by the enzyme triosephosphate isomerase (TPI), with TPI1 expression correlated with increased rates of proliferation in gastric cancer cells." (PMID 31737625, 2019). "Gastric cancer has been linked to deletion in malignant brain tumors 1 protein (DMBT1), triosephosphate isomerase (TPI1), and cyclostatin B (CSTB) Many target molecules, including extracellular RNA, amino acids, proteins, and glycoproteins have been the subject of studies on salivary biomarkers." (PMID 41245374, 2025). "Upregulation of TPI1 has been reported in gastric cancer and pancreatic cancer." (PMID 35246510, 2022). "One study has reported that TPI1 could promote cell proliferation and migration in gastric cancer with mechanism unclear; however, another study in liver cancer indicates that TPI1 inhibits tumor cell growth." (PMID 35246510, 2022). "TPI1 could also promote the metastasis of gastric cancer cell lines." (PMID 35246510, 2022). "Our analysis identified a range of biomarkers, highlighting three proteins - cystatin-B (CSTB), triosephosphate isomerase (TPI1), and deleted in malignant brain tumors 1 protein (DMBT1) - as particularly accurate for gastric cancer diagnosis." (PMID 39119128, 2024). "However, the combination of CSTB, TPI1, and DMBT1 proteins demonstrated the highest AUC value, indicating superior discriminative capacity between gastric cancer patients and healthy individuals." (PMID 39119128, 2024). "TPI1, an enzyme that catalyzes the interconversion of DHAP and G3P in glycolysis and gluconeogenesis, might be a novel prognostic factor to evaluate gastric cancer patients' survival." (PMID 33102573, 2020). "The combination of these three proteins, namely CSTB (cystatinB), TPI1 (triosephosphate isomerase), and DMBT1 (deleted in malignant brain tumour 1 protein) could distinguish gastric cancer cases with high accuracy." (PMID 31890650, 2019).
hepatocellular carcinoma (17 papers, 2010 to 2025). A malignant tumor that arises from hepatocytes. "When the glycolytic module (contains TPI1) is inhibited, there is a decrease in the S phase and an increase in the G2/M phase of the cell cycle and a decrease in the aggressiveness of hepatocellular carcinoma." (PMID 38102653, 2023). "It was also reported that TPI1 expression was greatly decreased in hepatocellular carcinoma." (PMID 35126788, 2022). "It has been found in hepatocellular carcinoma (HCC) cells that TPI1 inhibits growth, migration and invasion." (PMID 36361522, 2022). "Interestingly, overexpression of TPI1 in hepatocellular carcinoma cells impairs proliferation, suggesting the role of TPI may be cell type specific." (PMID 31737625, 2019). "When miR-193b-3p levels were increased, triosephosphate isomerase (TPI1) levels were decreased in both the plasma of T2DM patients and HepG2 hepatocellular carcinoma cells." (PMID 41303682, 2025). "TPI1 was recognized as a serum biomarker in patients with cancer, including BRCA, lung squamous cell carcinoma and hepatocellular carcinoma (HCC)." (PMID 35509067, 2022). "The overexpression of another metabolic marker, triosephosphate isomerase 1 (TPI1), a tumor suppressor, was observed in keratinized OSCC, suggesting a decline in tumor growth, as suggested in a previous study on hepatocellular carcinoma." (PMID 32922662, 2020).
lung carcinoma (14 papers, 2018 to 2025). "Recently, it was shown that accumulation of the glycolysis enzyme TPI1 in the nucleus is associated with poor prognosis and chemoresistance in lung cancer." (PMID 36996232, 2023). "Prior studies have shown that TPI-1 is overexpressed in lung cancer and plays a key role in tumorigenesis." (PMID 40190551, 2025). "Genes associated with cell immune functions were enriched in these pathways, such as COPS5, GSTM5, and TPI1, indicating the critical role of 5hmC modifications in immune response in lung cancer treatment." (PMID 38667328, 2024). "The high expression of TPI1 (triosephosphate isomerase 1), as a glycolysis-related gene, has been correlated with the low infiltration of lymphocytes in lung cancer and laryngeal squamous cell carcinoma." (PMID 38667328, 2024). "In mouse lung cancer cells, instead, there is a substitution of an oxidizable cysteine for serine at residue 21 of TPI1." (PMID 39544365, 2024). "In fact, this is supported by our observation that TPI1 prompts lung cancer cells proliferation, migration, and tumorigenesis independent of its enzymatic activity." (PMID 35246510, 2022). "Knocking down of TPI1 in lung cancer cells significantly reduced cell migration, colony formation, and xenograft tumor growth." (PMID 35246510, 2022). "Increased TPI1 expression was correlated with poor prognosis in lLUAD and changed immune cell infiltrating in various degrees in both types of lung cancers." (PMID 35126788, 2022). "First, TPI1 expression should be further tested in diverse lung cancer patient cohorts with different therapies." (PMID 35126788, 2022). "The relatively high TPI1 expression of LUSC was also confirmed using common lung cancer cell lines in CCLE (P = 0.032 and P = 0.050)." (PMID 35126788, 2022). "Further analysis on ALDH2, ALDH3a1, FBP1, PGD, TALDO1, and TPI1 as biomarkers on the evolution of IPF patients, their association with PJ infection, and their lung cancer risk could be relevant." (PMID 39997396, 2025). "Pathway enrichment analyses were performed to identify possible roles of TPI1 in both lung cancers." (PMID 35126788, 2022). "Based on in vitro model and serological proteome, TPI1 may be assumed as a potential biomarker in lung carcinoma." (PMID 35509067, 2022). "We found that TPI1 was significantly overexpressed in both types of lung cancers." (PMID 35126788, 2022). "The specific role of TPI1 in lung cancer development is unclear." (PMID 35246510, 2022). "TPI1 expression is higher in tissue and plasma of lung cancer patients than in cancer-free humans." (PMID 35509067, 2022). "Notably, significant nuclear accumulation of TPI1 has been observed in lung cancer tissues, and TPI1 nuclear translocation is induced by extracellular stress, such as chemotherapy drugs, which enhances chemoresistance in lung cancer cells." (PMID 41429797, 2025). "In addition, an increasing number of studies indicated that this gene influences glycolysis in target cells via different pathways, such as the METTL5/cMyc/TPI1 pathway, thereby affecting the onset and prognosis of various diseases, including lung cancer, liver cancer, and myopia." (PMID 40746540, 2025). "Furthermore, we compared TPI1 expression among common histological types of lung cancer." (PMID 35126788, 2022). "The specific role of TPI1 in lung cancer development is not completely clear but it has been described a significant correlation of TPI1 with poor prognosis, especially in LUAD." (PMID 39997396, 2025). "In support of this, TPI1 with a NLS, but not NES, significantly promotes migration and colony formation ability of lung cancer cells." (PMID 35246510, 2022).
melanoma (12 papers, 2019 to 2024). A malignant, usually aggressive tumor composed of atypical, neoplastic melanocytes. "Consistent with findings from our parental and dormant mouse melanoma models, a notable frequency of TPI1 amplification at both the diagnostic (4.7%) and metastatic (6.4%) stages was observed." (PMID 39223638, 2024). "Therefore, TPI1 RES probably also affected ICI treatment response in melanoma patients." (PMID 36969056, 2023). "In one study, TPI-1 analogs were tested, with analog TPI-1a4 found to inhibit growth of K1735 melanoma tumors in mice." (PMID 31293965, 2019). "TPI-1, a SHP-1-targeted anti-cancer agent, inhibited the growth of B16 melanoma tumors in ~83% of treated mice at a tolerated oral dose in a T cell-dependent manner." (PMID 31293965, 2019). "Interestingly, these authors also found that TPI-1 has anticancer potential on B16 melanoma thanks to the described induction of IFN-γ and demonstrated that B16 tumor growth is inhibited following TPI-1 treatment." (PMID 33003469, 2020).
lung adenocarcinoma (10 papers, 2007 to 2024). A carcinoma that arises from the lung and is characterized by the presence of malignant glandular epithelial cells. "We comprehensively explored and validated the TPI1 expression in lung adenocarcinoma and lung squamous cell carcinoma in public datasets." (PMID 35126788, 2022). "This analysis not only confirms genes that are known to be involved in tumorigenesis, but also reveals a significant correlation of triosephosphate isomerase 1 (TPI1) with poor prognosis, especially in lung adenocarcinoma (LUAD)." (PMID 35246510, 2022). "MiRNA hsa-mir-30a and lncRNA AC104472.1 constituted regulatory module for lung adenocarcinoma a with TPI1, KPNA2, MET, HSP90B1, P4HB, DSP, CDH1, and ENO1." (PMID 36138770, 2022). "Previous studies have reported TPI1 overexpression in lung adenocarcinoma and squamous cell carcinoma of the bladder." (PMID 23724044, 2013). "Surprisingly, it was reported that the translocation of TPI1 to cell nucleus could induce the chemoresistance of lung adenocarcinoma cells." (PMID 38102653, 2023). "Recent studies have shown that the expression level of triosephosphate isomerase 1 (TPI1) may be associated with the occurrence and metastasis of tumors, but the expression level of TPI1 and its effect on lung adenocarcinoma (LUAD) and squamous cell carcinoma (LUSC) are not yet clear." (PMID 35126788, 2022).
ovarian cancer (9 papers, 2010 to 2026). A primary or metastatic malignant neoplasm involving the ovary. "Reduction in or overexpression of TPI1 reduced or increased SHetA2 potency, respectively, in two ovarian cancer cell lines (t-tests; p < 0.05)." (PMID 41677630, 2026). "A previous study showed a higher expression of TPI1 in metastatic ovarian tumors than in primary ovarian cancers." (PMID 35610567, 2022). "In endometrial and ovarian cancers, the expression of TPI-1 and ENO1 was higher in metastatic tumors than in primary tumors; this finding was consistent with the reported role of these proteins in promoting tumor cell survival and proliferation." (PMID 23504277, 2013). "In endometrial and ovarian cancers, western blotting revealed that the expression of alpha-enolase (ENO1) and triosephosphate isomerase (TPI-1) was higher and the expression of Transgelin-2 (TAGLN2) was lower in metastatic tumors than in primary tumors." (PMID 23504277, 2013).
giardiasis (8 papers, 2013 to 2024). An infection of the small intestine caused by the flagellated protozoan giardia lamblia. "TPI1 is located in the cytoplasmic and extracellular regions, which is associated with triosephosphate isomerase deficiency and giardiasis." (PMID 35126788, 2022). "TPI1, which is also a protein-coding gene, is primarily associated with triosephosphate isomerase deficiency and giardiasis." (PMID 34233293, 2021). "TPI1 is primarily associated with triosephosphate isomerase deficiency and giardiasis." (PMID 35126788, 2022).
pancreatic cancer (8 papers, 2019 to 2025). "Studies on TPI1 have reported that the gene plays a role not only in colon cancer but also in pancreatic cancer." (PMID 34233293, 2021). "Our proteomic analysis of sera from an independent cohort of pancreatic cancer patients showed TPI1 as one of the most abundant protein in low survival patients before and after CT." (PMID 30873387, 2019). "Proteomic analysis of sera from pancreatic cancer patients showed TPI1 as one of the most abundant proteins in patients with poor survival before and after chemotherapy and could be further investigated as a prognostic marker as its levels gradually increase as the disease progresses." (PMID 32197468, 2020).